STIM2 (stromal interaction molecule 2)
Diseases named in the same sentence as STIM2 in open-access papers (continued):
Sharing a sentence is not in itself a finding about the gene and the disease.
colon carcinoma (6 papers, 2013 to 2020). "STIM2 was overexpressed in 64% of human colon cancers examined, but increased expression of STIM2 was significantly correlated with a less invasive phenotype, suggesting a tumor growth suppressing role of STIM2." (PMID 31252656, 2019). "The expression of STIM2 in human colon cancer HT29 cells was significantly lower than that in normal mucosa NCM460 cells." (PMID 31252656, 2019). "For example, in human colon cancer, a complex interplay between TRPC1/Orai1 and STIM2 was identified, with TRPC1/Orai1 expression upregulation being associated with increased SOCE and Ca2+ store content, whereas STIM2 downregulation underlying Ca2+ store depletion and promoting apoptosis resistance." (PMID 32872338, 2020). "In HT29 colon cancer cells, SOCE was significantly enhanced despite reduced Stim2 expression." (PMID 29783744, 2018). "Interestingly, we reported that colon cancer HT29 cells display enhanced STIM1 expression along decreased STIM2 expression relative to normal NCM460 colonic cells, thus, resulting in enhanced STIM1 to STIM2 ratio in cancer cells." (PMID 30642111, 2019).
colorectal cancer (5 papers, 2008 to 2023). A primary or metastatic malignant neoplasm that affects the colon or rectum. "The recent association of STIM2 with colorectal cancer also highlights the relevance of this family of proteins to molecular pathways that regulate cell proliferation and differentiation." (PMID 18950512, 2008). "This is similar to our previous studies in colorectal cancer cell lines showing that STIM2 has a large contribution to SOCE." (PMID 37778728, 2023). "In colorectal cancer cells the high STIM2 expression levels has been related with a reduced invasive phenotype, suggesting a cancer cell growth suppressor function in contrast to STIM1." (PMID 32733237, 2020). "The bigger contribution of STIM2 to SOCE might be a characteristic of some cancer cells as previous results showed larger contribution of STIM2 to SOCE in colorectal cancer cell lines." (PMID 37778728, 2023). "However, a recent study has identified STIM2 as a putative target of β-catenin/TCF in colorectal cancer (A. Villanueva, personal communication)." (PMID 18950512, 2008).
prostate carcinoma (5 papers, 2013 to 2024). A carcinoma that arises from epithelial cells of the prostate gland. "STIM2 abnormality was closely correlated with immune TME indicating of poor prognosis, and the dysregulation of STIM2 in the stroma region was associated with the more invasive clinical phenotype and poor outcome in prostate cancer." (PMID 39272139, 2024). "High expression levels of STIM2 was found in tumor stroma and epithelial tissues of human prostate cancer." (PMID 31252656, 2019). "We here summarize findings on gene expression levels and functions of SOCE components, stromal interaction molecules (STIM1 and STIM2), and members of the Orai protein family (Orai1, 2, and 3) in prostate cancer." (PMID 29951353, 2017). "However, downregulation of STIM2 in the stroma region was correlated with the transition from moderate-to-high Gleason grade, which is often used as a prognostic marker for prostate cancer." (PMID 31252656, 2019). "This article summarizes what is known about the dysregulation of the key molecular players involved in SOCE (STIM1, STIM2, Orai1, Orai2, and Orai3) and the negative regulator TRPM4 in prostate cancer." (PMID 29951353, 2017). "We compare expression levels of STIM1, STIM2, Orai1, Orai2 and Orai3 in tumorous and non-tumorous tissue from prostate cancer patients." (PMID 24240085, 2013). "We thus determined relative STIM and Orai expression levels in non-tumorous and tumorous tissue from 13 prostate cancer patients by qRT-PCR, from which 13 expressed detectable levels of STIM1, STIM2 and Orai1 and 11 detectable levels of Orai2 and Orai3." (PMID 24240085, 2013).
cervical cancer (4 papers, 2013 to 2021). A primary or metastatic malignant neoplasm involving the cervix. "STIM1 or STIM2 knockdown by different siRNA duplexes in cervical cancer SiHa cells was accompanied by a significant decrease of SOCE activation." (PMID 26917047, 2016). "Time-lapse fluorescent images of cervical cancer SiHa cells overexpressing fluorescently-tagged STIM1 or STIM2 were employed to study the dynamics of STIM proteins in SOCE activation." (PMID 26917047, 2016). "Regarding the role of STIM2 in cell cycle regulation, results from the individual or simultaneous silencing of STIM1/STIM2 in cervical cancer cells suggested that both STIM1 and STIM2 are involved in the regulation of SOCE during G1/S transition, and thus contribute to cell proliferation." (PMID 31252656, 2019). "Therefore, using the STIM1/STIM2 ratio as a marker of cervical cancer aggressiveness might be promising and worth further evaluation." (PMID 35008759, 2021). "Double knockdown of STIM1 and STIM2 also led to the accumulation of Cyclin E and decrement of CKD2 phosphorylation in cervical cancer SiHa cells." (PMID 26917047, 2016). "Regarding the role of STIM2 in cervical cancer cell proliferation, results from the individual or simultaneous silencing of STIM1/STIM2 suggested that both STIM1 and STIM2 contribute to the cell proliferation, at least partly through the regulation of SOCE during G1/S transition." (PMID 35008759, 2021). "However, a very recent study on cervical cancer SiHa cells showed that STIM1 and STIM2 displayed different kinetic characteristics during SOCE activation." (PMID 31252656, 2019). "Regarding STIM2, our recent study on a limited number of surgical specimens of cervical cancer showed a decreased tumoral STIM2 expression when compared with non-cancerous epithelium, whereas a higher tumoral STIM2 level when compared with invasive tumor front." (PMID 35008759, 2021). "However, this trend of redundancy between STIM1 and STIM2 expressions was not noted in cervical cancer patients, indicating the role of STIM2 in tumor biology may be tissue- or cell-type specific." (PMID 23594099, 2013).
Huntington disease (4 papers, 2018 to 2022). Huntington disease (HD) is a rare neurodegenerative disorder of the central nervous system characterized by unwanted choreatic movements, behavioral and psychiatric disturbances and dementia. "For instance, the neuronal SOCE enhancement with elevated STIM2 expression was seen in medium spiny neurons (MSNs) of YAC128 Huntington's disease (HD) mice, and inhibition of SOCE or knockdown of STIM2 improved dendritic spines deficiency in these mice." (PMID 32815315, 2020). "Unlike the AD setting, in the striatum from Huntington’s disease (HD) transgenic mice, an increased STIM2 expression causes elevated synaptic SOCE that was suggested to underlie synaptic loss in medium spiny neurons." (PMID 29623030, 2018). "The same group of researchers later demonstrated that in a juvenile form of Huntington’s disease, there was increased SOCE that was mediated by STIM2." (PMID 35821821, 2022).
glioblastoma (3 papers, 2014 to 2024). The most malignant astrocytic tumor (WHO grade IV). "In a genome-wide gene expression analysis of 20 primary glioblastoma samples, Stim2 expression was upregulated." (PMID 29783744, 2018). "The low expression of STIM1 and STIM2 drives glioblastoma (GBM) progression." (PMID 39272139, 2024).
Stroke (3 papers, 2018 to 2021). Sudden impairment of blood flow to a part of the brain due to occlusion or rupture of an artery to the brain. "In line with this concept, numerous in vitro studies have shown that STIM2 is implicated in ischemia-induced neuronal Ca2+ accumulation and deficiency of STIM2 confers protection against stroke in mice, likely through reduced Ca2+ accumulation into ER of neurons." (PMID 34685498, 2021). "The presently observed stimulation of ORAI1 and STIM2 could thus contribute to the known high risk of cardiac infarction and stroke in CKD patients." (PMID 32015442, 2020). "Accordingly, deficiency of STIM2 confers protection against stroke in mice." (PMID 29623030, 2018). "In fact, the lack of STIM2 abolishes variations in synaptic cholesterol content in neurons in response to high excitatory neurotransmission, a conditions occurring in stroke as well as in epilepsy and brain trauma (Müller and Connor, 1991)." (PMID 29623030, 2018).
Anxiety (2 papers, 2015 to 2020). Intense feelings of nervousness, tension, or panic often arise in response to interpersonal stresses. "Together, these results reveal no locomotor defects in these three mutant mice and a higher tendency for exploratory behavior (reduced anxiety) in the double Stim1/Stim2 cKO mice apparent in the EPM." (PMID 26236206, 2015). "The double Stim1/Stim2 cKO mice, however, spent more time in the open arms than their control littermates, suggesting an increased willingness for exploration and reduced anxiety-like behavior." (PMID 26236206, 2015). "Mice that overexpressed STIM2 and ORAI1 in neurons exhibited reductions of anxiety-like behavior, including increases in exploration of the arena in the open field test and time spent on the open arms of the elevated plus maze." (PMID 32455839, 2020).
autoimmune disease (2 papers, 2015 to 2020). A disorder resulting from loss of function or tissue destruction of an organ or multiple organs, arising from humoral or cellular immune responses of the individual to their own tissue constituents. "We previously showed that SOCE is essential for pathogenic Th17 cell function as mice with T cell‐specific deletion of ORAI1, STIM1 or STIM2 were protected in Th17 cell‐dependent animal models of autoimmune diseases such as EAE and colitis." (PMID 32609955, 2020). "We also note that loss of STIM2 correlates with reduced functions of SOCE and FcγR-mediated phagocytosis, indicating that STIM2 may contribute to some degree to cell destructive events in autoimmune diseases." (PMID 26417434, 2015).
cognitive decline (2 papers, 2018 to 2023). "Thus, disturbance of STIM2-SOCE-CaMKII pathway contributes to synaptic loss and cognitive decline; conversely, upregulation of STIM2 expression levels or activation of synaptic neuronal SOCE pathway may yield therapeutic benefits for the treatment of AD and other age-related memory disorders." (PMID 29623030, 2018).
colitis (2 papers, 2020 to 2022). Inflammation of the colon. "The histological analysis of intestinal inflammation showed severe colitis in host mice that had received wildtype or Stim2‐deficient CD4+ T cells, whereas inflammation was partially reduced or absent following transfer of Orai1‐deficient and Stim1‐deficient CD4+ T cells, respectively." (PMID 35919953, 2022). "Using a murine T cell transfer model of colitis, we show that deletion of the CRAC channel genes Stim1, Stim2, or Orai1 in T cells prevents IBD and that the severity of intestinal inflammation correlates with the level of SOCE." (PMID 35919953, 2022).
dermatitis (2 papers, 2020 to 2024). An inflammatory process affecting the skin. "Mice deficient in both Stim1 and Stim2 in T cells develop a lymphoproliferative disorder and dermatitis, characterized by eosinophilia and augmented IgE and IgG1 responses." (PMID 38578569, 2024). "For example, urolithin A, an ellagitannin metabolite, dose-dependently inhibited (10-50 μM) proliferation and activation of CD4+, by calcium influx impairment through the STIM1/STIM2–Orai1–SOCE pathway, but its effect on dermatitis is still unknown." (PMID 32575730, 2020).
Hypertension (2 papers, 2019 to 2025). The presence of chronic increased pressure in the systemic arterial system. "A variety of statistically significant genetic polymorphisms were identified that can be attributed to the heritability of varicose veins affecting inflammation and immunity (eg, PPP3R1, EBF1, and GATA2), hypertension (eg, CASZ1), and vascular architecture (eg, CASZ1, PIEZO1, and STIM2)." (PMID 41391741, 2025).
idiopathic pulmonary arterial hypertension (2 papers, 2012 to 2018). A sporadic form of pulmonary arterial hypertension (PAH) characterized by elevated pulmonary arterial resistance leading to right heart failure. "Interestingly an increase in the expression of STIM2 in PASMC was observed in idiopathic pulmonary arterial hypertension (IPAH) patients, which contribute to an augmentation of SOCE and enhancement of PASMC proliferation." (PMID 23056939, 2012). "Song and colleagues suggested that STIM2 contributes to SOCE in Pulmonary Artery Smooth Muscle Cells (PASMCs) from Patients with idiopathic Pulmonary Arterial Hypertension (iPAH)." (PMID 29618985, 2018).
ischemia (2 papers, 2016 to 2021). A hypoperfusion of the BLOOD through an organ or tissue caused by a PATHOLOGIC CONSTRICTION or obstruction of its BLOOD VESSELS, or an absence of BLOOD CIRCULATION. "In particular, STIM2 plays an important role in ischemia-induced neuronal damage, and its absence in knockout mice was shown to interrupt blood flow in the brain, thus decreasing the neuronal damage caused by ischemia." (PMID 27803687, 2016).
neuroblastoma (2 papers, 2018 to 2021). Neuroblastoma (NB) is the most common solid, extracranial childhood tumor. "The overexpression of HAP1A in the human neuroblastoma cell line SK-N-SH (i.e., a cellular model of HD (SK-N-SH HTT138Q)) led to the appearance of a pool of constitutively active SOC channels and an increase in the expression of STIM2 protein." (PMID 30455632, 2018).
Splenomegaly (2 papers, 2017 to 2018). Abnormal increased size of the spleen. "Knockout of the ER Ca2+ sensors STIM1 and STIM2 in mice resulted in splenomegaly and reductions in proliferation, cytokine secretion and NFAT nuclear translocation in T cells upon TCR engagement." (PMID 29445164, 2018).
amelogenesis imperfecta (1 paper, 2022). Amelogenesis imperfecta (AI) represents a group of developmental conditions affecting the structure and clinical appearance of the enamel of all or nearly all the teeth in a more or less equal manner, and which may be associated with morphologic or biochemical changes elsewhere in the body. "A total of 44 genes [42 genes in mice with single gene mutations and two additional genes (Bmp4 and Stim2) in compound mutant models] were identified in mice as genes associated with amelogenesis imperfecta through the systematic review." (PMID 35401675, 2022).
amyloid (1 paper, 2017). "In case of AD, overexpression of nSOC component STIM2 prevents mushroom spine loss in AD mouse models and in conditions of amyloid toxicity suggesting that downregulation of STIM2-nSOC pathway is a potential mechanism of synaptic loss in AD14,15,17." (PMID 29247211, 2017).
anemia (1 paper, 2015). A reduction in the number of red blood cells, the amount of hemoglobin, and/or the volume of packed red blood cells. "Indeed, STIM2-deficient mice showed no negative effect on 34-3C mAb-induced anemia in the clearance of MRBC as indicated by Ht levels and the percentage of liver cells containing ingested erythrocytes." (PMID 26417434, 2015).
autoimmune encephalitis (1 paper, 2021). Inflammation of the brain secondary to an immune response triggered by the body itself. "For example, knockout of STIM1 and STIM2 or ORAI1, key molecules controlling store operated Ca2+ entry, impaired the differentiation of Th1 and Th17 cells in vitro and in vivo, and protected mice from experimental autoimmune encephalitis." (PMID 34831261, 2021).
B cell lymphomas (1 paper, 2022). "As STIM1 and STIM2 differ in their expression profiles (at least in T cells) and the ER Ca2+ concentration to which they respond, this could potentially explain why only one of them, STIM2, showed a change in expression between CHL and other B cell lymphomas." (PMID 35685639, 2022).
Cerebral ischemia (1 paper, 2019). Restriction of arterial blood supply to the brain associated with insufficient oxygenation to support the metabolic requirements of the tissue. "Stim2 KO mice are better protected against cerebral ischemia compared with wildtype mice." (PMID 31075835, 2019).
colorectal adenocarcinoma (1 paper, 2024). The most common type of colorectal carcinoma. "By contrast, our results indicate that treatment of the colorectal adenocarcinoma cell lines with postbiotics of Lacticaseibacillus paracasei and Lactiplantibacillus plantarum did not significantly alter the protein content of Orai3 and STIM2." (PMID 38514909, 2024).
congenital heart defects (1 paper, 2023). "Several disorders have also been associated with STIM2 allele duplication or deletion, leading to STIM2 overexpression or absence, which are characterized by intellectual delay, microcephaly, physical and facial dimorphism, or congenital heart diseases." (PMID 37759684, 2023). "In addition, we summarize the current evidence concerning STIM2 allele duplication and deletion associated with language, intellectual, and developmental delay, recurrent pulmonary infections, microcephaly, facial dimorphism, limb anomalies, hypogonadism, and congenital heart defects." (PMID 37759684, 2023).
epilepsy (1 paper, 2020). A brain disorder characterized by episodes of abnormally increased neuronal discharge resulting in transient episodes of sensory or motor neurological dysfunction, or psychic dysfunction. "The overall results favor the view that CSMD1, STIM2, and RGS7BP genes could contribute to epilepsy and migraine phenotypes in our family." (PMID 32315120, 2020). "Thus, considering the oligogenic origin of epilepsies, it is reasonable to speculate that the detrimental effect of the rearrangement on CSMD1 and hypothetically STIM2, together with RGS7BP deletion may contribute to the epilepsy/migraine phenotypes in our family." (PMID 32315120, 2020).
familial Alzheimer disease (1 paper, 2016). A degenerative disease of the brain that causes gradual loss of memory, judgment, and the ability to function socially. "Disturbances in STIM2-associated pathways have also been observed in lymphocytes in familial Alzheimer’s disease, brain tissue in ageing mice and humans who suffer from sporadic Alzheimer’s disease." (PMID 27826230, 2016).
glaucoma (1 paper, 2024). Increased pressure in the eyeball due to obstruction of the outflow of aqueous humor. "Our study suggests a novel role for Stim2 in the regulation of neuronal insulin expression and GABAergic-dependent vision causing glaucoma-like retinal pathology." (PMID 39424970, 2024). "Altogether, our results suggest that zebrafish depleted of Stim2 is a suitable model to investigate glaucoma-related changes." (PMID 39424970, 2024). "In conclusion, our study elucidates the multifaceted role of Stim2 in neuronal gene regulation and cellular physiology, offering insights into its involvement in shaping neuronal connectivity and potential implications for glaucoma pathophysiology." (PMID 39424970, 2024). "However, our observation that lack of Stim2 in zebrafish induces changes in retina similar to those observed in glaucoma have some limitations." (PMID 39424970, 2024).
hepatoma (1 paper, 2023). "In hepatoma cells, ORAI1 and STIM2 adapter protein were the predominant forms, while in HepaRG cells, transcription of ORAI3 and STIM1 was much higher, as revealed in RNAseq dataset and by real-time PCR." (PMID 37189460, 2023).
lung adenocarcinoma (1 paper, 2021). A carcinoma that arises from the lung and is characterized by the presence of malignant glandular epithelial cells. "Likewise, the in vitro, treatment with CDDP enhanced Orai3, but not Orai1 nor STIM1 or STIM2 expression in two lung adenocarcinoma cell lines: A549 and H23 cells." (PMID 34065942, 2021).
lupus nephritis (1 paper, 2025). Glomerulonephritis in the context of systemic lupus erythematosus. "Studies have demonstrated significantly elevated expression of Stim2 and Orai1 in lupus nephritis, and intervention with Orai1-specific small interfering RNA (siRNA) has been shown to markedly alleviate renal damage." (PMID 40989817, 2025).